BCL2 (BCL2 apoptosis regulator)
Diseases named in the same sentence as BCL2 in open-access papers (continued):
Sharing a sentence is not in itself a finding about the gene and the disease.
tumor (continued). "The extent of bcl-2 expression by tumour cells decreased significantly with respect to increasing tumour size (P < 0.05), decreasing lymphocytic infiltration (P < 0.05) and chance of poor clinical outcome (P < 0.05), but not with worsening of Dukes stages." (PMID 7547253, 1995). "Of ten borderline samples, one was unstained and five had weakly and four strongly bcl-2 positive tumour cells." (PMID 7577491, 1995). "Bcl-2 was expressed in 20% of tumours and it was related to small tumour size (P < 0.0001), low T category (P < 0.0001), lack of venous invasion (P = 0.008), node negativity (P = 0.015) and absence of metastasis (P = 0.017)." (PMID 7710955, 1995). "In vivo, TEN significantly suppressed tumor growth by decreasing Ki67 and BCL2 expression." (PMID 42110557, 2026). "In addition, MAL reduces mitochondrial membrane potential and promotes mitochondrial-mediated apoptosis through the BAX/Bcl-2/caspase-3 axis, further amplifying endogenous apoptosis in tumor cells." (PMID 41669875, 2026). "Ki‐67 and Bcl‐2 expression levels were reduced while Bax expression was enhanced after CA treatment, indicating that CA could suppress tumor proliferation and promote apoptosis in nude mice." (PMID 41513589, 2026). "The majority of identified lncRNAs regulate TRAIL (tumor necrosis factor-related apoptosis-inducing ligand)-mediated apoptosis by either promoting or inhibiting the expression of Bcl-2, contributing to heightened tumor growth, increased metastatic potential, and enhanced resistance to chemotherapy." (PMID 41276852, 2025). "In this respect, HIF-1α may induce the increased expression of VEGF, glycolytic enzymes, IGF2, and Bcl-2 genes, which facilitate the tumor cells’ adaptation to the hypoxic tumor microenvironment, by stem cells’ survival." (PMID 40227577, 2025). "Patients with BCL2-positive tumors (44/254) prior to treatment (either radiation, cisplatin monotherapy, or both) had shorter overall and progression-free survival (log-rank; p = 0.048) and a higher rate of tumor relapse (Fisher's exact test; p = 0.0032)." (PMID 39970625, 2025). "For instance, dual CAR‐T therapies targeting EGFRvIII on tumor cells alongside senescent cell markers like p16INK4a or Bcl‐2 may enhance anti‐tumor efficacy by reducing senescent cells that contribute to tumor growth and immunosuppression." (PMID 40178455, 2025). "The mechanism is mainly twofold: first, by upregulating γH2AX expression, it enhances radiation-induced DNA double-strand breaks, thereby increasing tumor cell damage; second, by increasing the Bax/Bcl-2 ratio and activating Caspase-3 expression, it promotes tumor cell apoptosis." (PMID 41367875, 2025). "On the contrary, 4-methylchalcone is not able to hydrogen bonding, but another type of interaction within the interacting amino acids on chain A is quite sufficient to achieve a similar docking score (−52.09/0.10) and the quality of milder inhibitor of BCL-2 tumor target." (PMID 40331930, 2025). "Notably, the tumor cells co-expressed Bcl-2 (95%) and c-Myc (70%), meeting the criteria for double expressor lymphoma (DEL), suggesting aggressive biological behavior." (PMID 41229502, 2025). "Bcl-2 has been reported to play an important role in paclitaxel-mediated apoptosis and anti-tumor pathway, therefore, it is an important effector protein in paclitaxel-mediated tumor chemotherapy." (PMID 41315221, 2025). "At the molecular level, the anti-apoptotic proteins Bcl-2/Bcl-xl enable tumor cells to evade programmed cell death by suppressing mitochondrial apoptosis, while the Akt/mTOR signaling pathway promotes tumor growth, metabolic reprogramming, and survival signals." (PMID 40363681, 2025). "Autophagy also regulates tumor suppression through the interaction between Beclin-1 and Bcl-2." (PMID 40688079, 2025).
tumor (continued). "This indicates that DE mediated ferroptosis activation and stemness inhibition, as well as enhancing caspase 3-dependent apoptosis and lowering the protein level of the key oncogene, BCL-2, and ultimately this nanocomplex significantly suppressed primary and secondary tumor growth." (PMID 39888413, 2025). "Furthermore, AKT played key roles in the cell apoptosis-inducing and anti-tumor effects of LNT via the Nur77/Bcl-2 pathway." (PMID 39744474, 2025). "Specifically, pro-apoptotic Bax promotes the cytosolic release of cytochrome C and activates one of the key executioners of apoptosis, Caspase-3, leading to apoptosis, while the down-regulation of anti-apoptotic protein Bcl-2 indicates the release of apoptosis suppression in tumor cells." (PMID 41012539, 2025). "Obatoclax functions as a pan–BCL‐2 inhibitor that promotes apoptosis by neutralizing antiapoptotic proteins, while leflunomide suppresses tumor proliferation through inhibition of dihydroorotate dehydrogenase, thereby impairing pyrimidine synthesis and cell‐cycle progression." (PMID 41438620, 2025). "Since signalling pathways such as Akt and ERK directly modify Bcl-2 and beclin-1, the resulting phospho-patterns may predict the tumour’s responsiveness to upstream kinase inhibitors." (PMID 41511337, 2025). "Additionally, the immunohistochemical staining of the tumor sections provided visual confirmation of reduced BCL-2 protein levels in the DNZ-treated groups." (PMID 40643466, 2025). "Even a small population of BCL-2+ cells may eventually dominate in the pathological tumor environment due to greater resistance to apoptosis." (PMID 40699745, 2025). "Overexpression of Bcl‐2 in tumors may lead to resistance of cancer cells to apoptosis, thereby promoting tumor growth and survival." (PMID 41142018, 2025). "Concurrently, miR-34a targets BCL2, thereby promoting apoptosis and reducing tumour cell survival." (PMID 40978098, 2025). "Targeting CD37 and its downstream effector BCL2 may enhance the anti-tumor efficacy, thereby improving the effectiveness of immunotherapy." (PMID 40250439, 2025). "This limitation may result from tumor cell resistance to FLT3 inhibitors and the limited ability of BCL-2 inhibitors to induce apoptosis in tumor cells, which relies on alternative antiapoptotic pathways." (PMID 40016600, 2025). "Moreover, tumor cells in the lymph nodes seem to show a higher expression of anti-apoptotic BCL-2 proteins in comparison with tumor cells in the peripheral blood." (PMID 40864758, 2025). "We propose that the predicted interaction between zma-miR156a-3p and BCL2 could represent a beneficial regulatory mechanism capable of fighting cancer progression, especially considering the established role of BCL2 in tumor cell survival." (PMID 41440174, 2025). "Moreover, treatment with exomiR-34a decreased tumor growth in a xenograft mouse model by reducing Ki67 and Bcl-2 levels and increased apoptosis within tumor tissues." (PMID 40699746, 2025). "To investigate whether tumor suppression was mediated by BCL-2 silencing, we performed a molecular analysis on excised tumor tissues collected 21 days post-treatment." (PMID 40643466, 2025). "PTEN is a classic tumor suppressor gene while BCL2, BAX and Caspase-3 are regulators of apoptosis." (PMID 40457415, 2025). "With the increaseof these ceramide species in serum, the BAX/BCL2 ratio increases in tumour tissue." (PMID 40821650, 2025).
tumor (continued). "A recent study in NSCLC further revealed that CIP2A binds to pyruvate kinase M2 (PKM2), inducing tetramer formation, redirecting PKM2 to mitochondria, and enhancing oxidative phosphorylation and B-cell lymphoma 2 (Bcl-2) phosphorylation—thereby boosting tumor cell energy metabolism and survival." (PMID 40943297, 2025). "Although some scholars believe that high expression of Bcl-2 may be regarded as a good prognostic factor, it may vary with tumor type, stage, and individual differences." (PMID 40507857, 2025). "Histological analysis indicated typical tumor morphology (H&E staining) alongside enhanced expression of the pro-apoptotic marker Caspase-3 and Bax and decreased expression of the anti-apoptotic protein Bcl-2 in HPX-overexpressed tumors compared to controls." (PMID 41008813, 2025). "In animal models, the combination of ZD55-SATB1 and DTX significantly reduced tumor growth, increased pro-apoptotic factors such as caspase-3 and caspase-8, and decreased levels of anti-apoptotic proteins such as Bcl-2, along with reductions in angiogenic markers (CD31)." (PMID 40071088, 2025). "Finally, hsa_circ_0009109 promoted tumor growth and induces autophagy by targeting the miR-544a-3p/Bcl-2 axis." (PMID 40936702, 2025). "Tumor cells attain apoptosis resistance by down-regulating Bax and up-regulating Bcl-2." (PMID 40006525, 2025). "Importantly, the responsiveness of malignant tumor cells to apoptosis can be enhanced through either diminishing Bcl‐2 protein expression or suppressing Bcl‐2 functionality." (PMID 40405831, 2025). "This is consistent with its anti-apoptotic role and suggests that Bcl-2 may contribute to enhanced cell survival and tumor progression in these tissues by inhibiting programmed cell death." (PMID 40943673, 2025). "BCL-2 is an anti-apoptotic protein, and its overexpression may induce radioresistance in tumor cells." (PMID 40647527, 2025). "Furthermore, IL-4 facilitates immune evasion by upregulating anti-apoptotic proteins such as Bcl-2 and Bcl-xL, promoting tumor cells’ survival and resistance to apoptosis." (PMID 40864740, 2025). "DEL is defined as the expression of both Bcl-2 and c-Myc proteins at high levels in tumor cells." (PMID 41229502, 2025). "For instance, multiple tumor-suppressive miRNAs target anti-apoptotic factors like BCL-2, while distinct oncogenic miRNAs may enhance cell survival through parallel routes." (PMID 40429954, 2025). "Consistent with its role in apoptosis modulation, 4-MU significantly altered critical regulators of cell death in H22 tumor-bearing mice: Bax expression progressively intensified with escalating drug concentrations, whereas Bcl-2 expression exhibited reciprocal attenuation." (PMID 40839202, 2025). "One prominent example is the expression of genes encoding the BCL-2 family of anti-apoptotic proteins – BCL2, MCL1 and XIAP – which is enhanced by CDK9 activity and thereby enables cancer cell survival in a wide range of tumour types, including prostate cancer [,87]." (PMID 40163908, 2025). "By modifying the tumor microenvironment and promoting immune cell infiltration, Bcl-2 inhibition may enhance responses to immune checkpoint inhibitors, unlocking new potential for immuno-oncology strategies." (PMID 40841912, 2025). "Bax and Bcl-2 levels for 3d, 5a, and Staurosporine on human breast (MCF-7) cancer cell line." (PMID 41036428, 2025).
tumor (continued). "The overactivated IFN-γ and IFN-α axes converge to drive pathological antigen presentation and reactivation of the pathways, creating a vicious cycle that sustains downstream targets (STAT, MYC, Bcl-2, Bcl-xL), facilitating tumor cell proliferation, migration, and drug resistance." (PMID 40990011, 2025). "Oncoprotein BCL2 is essential for tumor development and the activation of the immune system." (PMID 39735667, 2025). "This system, based on a magnetothermal nanoparticle platform, utilizes the mild thermal effect (42°C) generated by an alternating magnetic field to activate the CRISPR-Cas9 system, thereby precisely targeting the HSP70 and BCL2 genes and significantly enhancing tumor cell apoptosis." (PMID 40297581, 2025). "They found that luteolin suppressed the proliferation rate, enhanced the cisplatin‐induced downregulation of Bcl‐2 expression, suppressed the migration and invasion stages whereas in vivo study, luteolin also lowered tumor growth and induced apoptotic cellular deaths." (PMID 39830909, 2025). "Furthermore, tumor cell apoptosis was assessed by quantifying apoptosis markers, specifically Bax and Bcl-2, within the tumor mass of mice administered various formulations." (PMID 41583493, 2025). "Additionally, flavones in fruit regulate apoptosis by decreasing the Bcl-2/Bax ratio and suppressing NF-κB activation, thereby reducing pro-inflammatory cytokine production and tumor progression." (PMID 41487662, 2025). "The cut-off value for positive expression of BCL-2 is 70% or more of tumor cells expressing BCL-2." (PMID 40098696, 2025). "Additionally, B‐cell lymphoma 2 protein and tumor growth were suppressed, while Bcl‐2 and p‐c‐Jun N‐terminal kinase protein were improved by anthocyanins." (PMID 40321606, 2025). "In hepatocellular carcinoma, PCSK9 exhibits dual roles: it can promote tumor growth by inhibiting apoptosis through the Bax/Bcl-2/Caspase pathway and also acts as a tumor suppressor by interacting with GSTP1 and inhibiting the c-Jun n-terminal kinase signaling pathway." (PMID 40764605, 2025). "BA treatment slightly increased Bax and Caspase-3 levels while decreasing Bcl-2 expression, consistent with studies showing that betulinic acid suppresses tumor growth through activation of mTOR-regulated apoptotic signaling and modulation of the Bax/Bcl-2/caspase axis." (PMID 41470183, 2025). "PTEN is a tumor suppressor gene while BCL2, BAX and Caspase 3 are apoptosis-related genes." (PMID 40457415, 2025). "Indeed, a similar approach with a static binding algorithm has been conducted with lupeol in the context of intracellular tumor promoting proteins, such as mTOR, topoisomerase, Bcl-2, and PI3K." (PMID 41303616, 2025). "Additionally, Notch1 activation stimulates tumor cell growth and enhances survival by regulating the expression of cyclins (such as Cyclin D1) and anti-apoptotic proteins (such as Bcl-2)." (PMID 40621472, 2025). "It follows that bilirubin may induce apoptosis in tumor cells by upregulating Bax and downregulating Bcl-2." (PMID 40291905, 2025). "In its Phase I trial in patients with advanced solid tumors, MRX34 demonstrated target engagement and tumor-suppressive activity (with downregulation of BCL2, MET, MYC) at tolerated doses, but the trial was ultimately discontinued due to immune-mediated adverse events." (PMID 41226828, 2025). "Bcl-2 and Bax play crucial roles in regulating apoptosis in tumor cells." (PMID 40181963, 2025). "In this context, our findings support a model in which PMAIP1 can promote mitochondrial apoptosis via the Bax/Bcl‐2 axis and ROS‐mediated dysfunction in vitro, but its clinical link to poor outcomes reflects context‐dependent regulation within the tumor microenvironment." (PMID 41476687, 2025). "Moreover, the expressions of pro-apoptotic proteins Bax and cleaved caspase 3 were elevated, and the anti-apoptotic protein Bcl-2 was decreased by DC in tumor tissue." (PMID 41019996, 2025).
tumor (continued). "In addition, CPT has been shown to inhibit tumor cell apoptosis by promoting tumor neovascularization, clearing toxic lipid metabolites, and activating the Bcl-2 protein." (PMID 41421797, 2025). "Furthermore, they modulate the apoptotic regulatory pathway by upregulating Bax and downregulating Bcl-2, thereby enhancing pro-apoptotic activity and inhibiting tumor cell survival." (PMID 40573220, 2025). "Anti-apoptotic proteins such as Bcl-2 and Bcl-xL prevent mitochondrial disruption by sequestering pro-apoptotic members, while inhibitor of apoptosis proteins (IAPs) directly inhibit caspases, allowing tumor cells to evade programmed cell death." (PMID 40765826, 2025). "Our findings demonstrated that 9c effectively inhibited tumor malignancy through cell cycle arrest and apoptosis induction with the transcriptional downregulation of anti-apoptotic genes including survivin, Mcl-1, Bcl-2, and XIAP." (PMID 40076615, 2025). "Moreover, genistein interferes with the function of specific cyclin/CDK complexes and modulates the activation of Bcl-2/Bax and caspases, playing a critical role in halting tumor cell division and promoting apoptosis." (PMID 39940882, 2025). "Luminal tumours are generally less aggressive, exhibit slower proliferation, higher differentiation status, and often retain functional cell cycle and apoptotic regulatory mechanisms (such as p21 activity or higher Bcl-2 expression)." (PMID 40469194, 2025). "Among these, the expression levels of beclin-1 and Bcl-2 are particularly informative, as their relative abundance and the stoichiometry of their interaction can indicate whether a tumour is more likely to rely on autophagy or apoptosis during therapy." (PMID 41511337, 2025). "Notably, SGs sequester pro-apoptotic mRNAs, such as BAX and CASP3, inhibiting their translation while stabilizing the expression of anti-apoptotic proteins, including BCL2, to ensure the survival of tumor cells." (PMID 41029457, 2025). "Given this condition, functionally blocking FGF19 and BCL-2 can restore tumor cell apoptosis." (PMID 39334936, 2024). "The expressions of Bax, Bcl-2, caspase 8, and caspase 3 in tumor cells were measured using qPCR." (PMID 39062024, 2024). "Furthermore, overexpression of miR-182 inhibits proliferation and induces apoptosis via targeting PBX3 and BCL2, suggesting that miR-182 acts as a tumor suppressor gene in ALL cells." (PMID 38528641, 2024). "Overexpression of BCL-2 promotes tumour growth and chemoresistance." (PMID 39816318, 2024). "However, all the other treatments upregulated the Bcl2 gene expression compared to the control untreated EST-tumor group." (PMID 38253759, 2024). "Furthermore, when compared to the CHMm+NK group, the CHMm+RNK group displayed a significant increase in the positive rates of Caspase 3 and BAX cells in tumor tissue, along with a significant decrease in the positive rates of BCL-2 and GPX4." (PMID 38891683, 2024). "Furthermore, Bcl-2 and Bcl-xL expression inhibits the normal apoptotic program of tumor cells and promotes their survival and development." (PMID 38572238, 2024). "Furthermore, the delicate equilibrium between pro- and anti-apoptotic BCL2 proteins determines the propensity of tumor cells to undergo apoptosis." (PMID 38482171, 2024). "Therefore, the combination can also deliver improved anti-tumour benefit in vivo in BCL2-positive chemotherapy refractory DLCBL malignancies." (PMID 39284898, 2024).